FOS (Fos proto-oncogene, AP-1 transcription factor subunit)
Diseases named in the same sentence as FOS in open-access papers (continued):
Sharing a sentence is not in itself a finding about the gene and the disease.
gastric cancer (42 papers, 2008 to 2025). A primary or metastatic malignant neoplasm involving the stomach. "We note that key nodes such as COL1A1, COL1A2, JUN, MMP9, APOE, and FOS displayed strongest strength of interactions in the network, suggesting that these genes are key genes associated with other proteins in gastric cancer." (PMID 39044041, 2024). "For example, lncRNA CRART16 promoted the formation of blood vessels in patients through the miR-122-5p/FOS axis, which can be regarded as a prognostic factor for gastric cancer." (PMID 38627627, 2024). "The authors found a subgroup of cells between the metastatic group and primary group and discovered some gastric cancer lymph node metastasis marker genes (ERBB2, CLDN11, and CDK12), as well as potential gastric cancer evolution-driving genes (FOS and JUN)." (PMID 37612741, 2023). "In conclusion, linc01133, a JUN and FOS regulated lncRNA, promoted gastric cancer cell growth as a ceRNA for miR-145-5p via YES1 mediated YAP1 nuclear translocation." (PMID 35017464, 2022). "In gastric cancer, “genome-wide screenings” were carried out where RelA and FOS proteins were identified as targets of miR-7; repressing the expression of these proteins in turn prevented proliferation and tumorigenesis in gastric cancer cells." (PMID 36012357, 2022). "FOS gene and Wnt family member 7B (Wnt7B) were found to be enriched in the Wnt signaling pathway in gastric cancer." (PMID 33373316, 2020). "The highest expression level gene of gastric cancer patients was FOS, in which the median expression level was 5007.70, and the maximum and minimum values were 73122.70 and 198.40." (PMID 32963532, 2020). "For instance, consistent with our findings, FOS has been shown to be downregulated after Twist depletion in gastric cancer cells." (PMID 26360779, 2015). "The absence of FOS expression is associated with advanced stage, lymph node metastasis, lymphatic invasion, and shorter survival, indicating its loss during gastric cancer progression and its correlation with poor prognosis." (PMID 39495117, 2024). "Furthermore, we detected the expression of c-JUN and c-FOS by immunohistochemistry (IHC) on human gastric cancer tissues." (PMID 35017464, 2022). "In addition, the miR-122-5p mimics or FOS siRNAs reversed bevacizumab resistance induced by CRART16 overexpression in gastric cancer cells (*P < 0.05)." (PMID 35537818, 2022). "Targeting on FOS and Wnt signaling can inhibit gastric cancer proliferation." (PMID 33373316, 2020). "In gastric cancer datasets, MT2A, TXNIP, FOS, RHOB, and GLUL emerged as the five most important mRNAs to predict exmiRs." (PMID 39495117, 2024). "For example, lncRNA CRART16 promotes gastric cancer angiogenesis by sponging miR-122-5p to upregulate FOS/VEGFD expression, and is a prognostic marker and therapeutic target for gastric cancer." (PMID 39198393, 2024). "Compared with the negative control cells, CRART16-overexpressing gastric cancer cells expressed a lower level of miR-122-5p and higher FOS and VEGFD (*P < 0.05)." (PMID 35537818, 2022). "Besides, the sequencing data showed that FOS and VEGFD expression were upregulated in CRART16-overexpressing gastric cancer cells." (PMID 35537818, 2022). "FOS and JUN overexpression increased linc01133 mRNA level in MKN45, SGC7901 and HGC27 gastric cancer cells, but not in AGS cells." (PMID 35017464, 2022). "Simultaneous overexpression of JUN and FOS leads to stably increased linc01133 expression in MKN45, HGC27 and SGC7901 but not in AGS gastric cancer cells." (PMID 35017464, 2022).
lung carcinoma (42 papers, 2008 to 2026). "The computational techniques used here revealed that CDKN1C and FOS, which are down-regulated genes in lung cancer-positive patients, are closely associated with the compulsive situation and are responsible for the regulation number of biological comebacks." (PMID 32318583, 2020). "On the other hand, reports on the FOS maintained that its down-regulation might be associated with the pathogenesis of lung cancer." (PMID 32318583, 2020). "Similarly, an increase in c‐FOS expression was observed in lenalidomide‐treated non‐small‐cell lung cancer cells and is speculated to be a mechanism underlying the relative insensitivity of lung cancer to lenalidomide." (PMID 37581569, 2023). "ID1 has been shown to promote migration of lung cancer cells, and FOS was reported to regulate inflammatory response during acute lung injury." (PMID 36762475, 2023). "FOS (Fos proto-oncogene, AP-1 transcription factor subunit) can induce the abnormal proliferation of lung cancer cells." (PMID 35807355, 2022). "The significant role of FOS gene is also identified in other cancers, such as bladder cancer, lung cancer, and colon cancer." (PMID 32280695, 2020). "Previously, CDDO-Me and CDDO-Im were shown to increase the expression of JUN (1 μM; H157 cells (2–8 h)) and FOS (0.2 μM (6 h)) in human lung cancer cells and HUVEC, respectively." (PMID 31523389, 2019). "More study should focus on the relationship between FOS and lung cancer to explore the mechanism between FOS and lung cancer." (PMID 28148898, 2017). "Similarly, IL-7 enhances bladder cancer invasion through NF-κB-mediated MMP-9 expression and promotes lung cancer proliferation by upregulating cyclin D1 via the c-FOS/c-Jun pathway." (PMID 41596598, 2026). "Mechanistically, ADAR1 may promote proliferation, invasion, migration, and tumorigenesis in lung cancer cells via the ERK/c-FOS/MMP-9 axis." (PMID 41309247, 2025). "In the previous study on FOS and lung cancer, some of the results were contradictory." (PMID 28148898, 2017). "The demonstration of the potential medical value of GTSE1, NMU, FOS, and CDKN1C in the prognosis of patients suffering from lung cancer was done by us in order to verify the levels of expression of FOS, CDKN1C, NMU, and GTSE1." (PMID 32318583, 2020). "We strongly believe that GTSE1, NMU, FOS, and CDKN1C have potential and clinical application values to act as prognostic markers of lung cancer." (PMID 32318583, 2020). "Based on our results, we found potential and prospective clinical applications in GTSE1, NMU, FOS, and CDKN1C to act as prognostic markers in case of lung cancer." (PMID 32318583, 2020). "Analyzing the mRNA expression microarrays showed FOS, GTSE1, CDKN1C, and NMU are greatly harbored by the patients of lung cancer and are observed to be differentially expressed (fold change ≥2.0) of these genes." (PMID 32318583, 2020). "Besides, NT157 decreased expression of oncogenes BCL2, CCND1, MYB, and MYC and increased genes related to cellular stress and apoptosis, JUN, BBC3, CDKN1A, CDKN1B, FOS, and EGR1 (p < 0.05), favoring a tumor-suppressive cell signaling network in the context of lung cancer." (PMID 36224313, 2022). "Indeed, in both H358 lung cancer and BxPC3 pancreatic cancer cells, MLN4924 induced PD-L1, and at the same time the phosphorylation of ERK1/2, AKT and JNK kinases as well as c-FOS in dose- and time- dependent manners, indicating the activation of these signaling pathways." (PMID 36192389, 2022).
lung carcinoma (continued). "Additionally, CDKN1C, GTSE1, NMU, and FOS are not correlated with one another, which indicates that every target can individually be cast off as a predictive marker for lung cancer." (PMID 32318583, 2020). "Finally, RNA profiling of lung epithelial cells (BEAS-2B) expressing a mutant allele of PIK3 (E545K) identified a network of transcription factors such as MYC, FOS and HMGA1, not previously recognised to be associated with aberrant PI3K signalling in lung cancer." (PMID 22363436, 2012).
prostate carcinoma (42 papers, 2008 to 2026). A carcinoma that arises from epithelial cells of the prostate gland. "To gain insight into the molecular consequences of the loss of Fos, we inactivated FOS by CRISPR/Cas9 in human prostate cancer cell lines." (PMID 34548912, 2021). "Intriguingly, the AP-1 subunit FOS exhibits decreased expression during the development of prostate cancer, similar to what is observed for GR." (PMID 39027480, 2024). "Phosphorylation of PXN activated ERK/ELK1 and increased the transcription of c-FOS and cyclin D1, which in turn facilitated the proliferation of prostate cancer cells." (PMID 36923874, 2023). "We found groups that contained within them known associations among the transcription factors associated with prostate cancer-relevant signaling pathways, such as JUN and FOS, both member of the MAPK signaling pathway (oTFCG3)." (PMID 30314329, 2018). "We have shown that NFκB can increase expression of FOS in prostate cancer cells and thus AP-1 activity." (PMID 22389719, 2012). "Lamin A/C appears as a member of a set of genes with reduced expression for higher grade primary prostate cancer samples (note that the current analysis that gave FOS as a biomarker is on lymph node metastatic samples like here)." (PMID 20805891, 2010). "These novel interactions between LMNA and FOS, their putative role in prostate cancer metastasis and their seemingly different behaviours in prostate cancer lymph node metastases warrant further investigation." (PMID 20805891, 2010). "The high rank of FOS was unexpected, but perhaps it is less of a surprise for some experienced researchers in prostate cancer as its role has been highlighted in the past." (PMID 20805891, 2010). "Amplification of members of the MAPK pathway was associated with androgen independent prostate cancer, and co-expression of RAF1, ERBB2/HER2 and c-FOS would lead to this phenotype." (PMID 20805891, 2010). "The proto-oncogenes JUN and FOS are pivotal in prostate cancer progression and invasion." (PMID 35508982, 2022). "Indeed, orthogonal validation of the FOS and FGF7 5′-UTR mutations in human prostate cancer cells revealed that these single-nucleotide alterations identified through PLUMAGE were sufficient to increase gene-specific transcript levels." (PMID 34244513, 2021). "In addition, motif analyses on accessible chromatin regions by FAIRE-seq identified motifs for a large range of other transcription factors previously linked to prostate cancer development and progression, including CTCF, SP1, FOS, and ETS domain family of transcription factors." (PMID 26412853, 2015). "Seven genes (ATM, BCL2, ERN1, FOS, NRAS, PIK3R1, and SP1) were regulated in opposite directions in patients with HD and prostate cancer." (PMID 37298337, 2023). "Mutations that impact transcript levels were found in oncogenic genes such as FOS (chr14: 75745674, C -> G) and FGF7 (chr15: 49715462, C -> T), which are components of the MAP kinase signaling pathway and known to drive prostate cancer pathogenesis 34,35." (PMID 34244513, 2021). "We analyzed expression of FOS and JUNB in human prostate cancer datasets and observed decreased expression in advanced stages." (PMID 34548912, 2021). "In this figure, there are two probes that are immediately recognizable by any cancer researcher, and in particular for those in prostate cancer: KLK3/PSA (Prostate Specific Antigen) and FOS." (PMID 20805891, 2010). "A 5-gene recurrence predictor of prostate cancer contains KLF6, three common ARACNe-based predictions between MYC and KLF6 (FOS, JUNB and ZFP36), and PPFIA3, which is functionally related to another predicted target of KLF6 (PPFIBP2)." (PMID 18190704, 2008). "In addition, it is possible that FOS, which is frequently overexpressed in severe prostate tumor, and FOSL1, which promotes growth and metastasis of prostate cancer cells, are also involved in castration-resistance acquisition." (PMID 37463954, 2023).
prostate carcinoma (continued). "Previous research has shown that in prostate cancer cell lines, a lack of FOS promotes cell proliferation and results in changes to oncogenic pathways." (PMID 36698183, 2023). "Also, ablation of FOS potentiates Jun expression, and CRISPR/Cas9-mediated KO of Jun constrains prostate cancer cell proliferation." (PMID 35508982, 2022). "We will not discuss in depth the known relationships between FOS, Lamin A/C and prostate cancer." (PMID 20805891, 2010). "At the same time, prostate cancer LNCaP and PC3 cells did not respond to FB significantly in terms of TFs expression, with exception of DU145 demonstrating just +3-fold upregulation of FOS (p<0.05)." (PMID 39318629, 2024).
melanoma (34 papers, 2008 to 2025). A malignant, usually aggressive tumor composed of atypical, neoplastic melanocytes. "Melanoma cells have a well-defined stressed cell state, which is marked by the upregulation of immediate early transcription factors (JUN, FOS, ATF3, NR4A1, DUSP) linked to melanoma oncogenic programs, inflammation, and stress response." (PMID 36765834, 2023). "As in humans, we also found that expression of zebrafish FOS orthologs is induced by oncogenic BRAF-ERK signalling in zebrafish melanomas." (PMID 36077499, 2022). "PBX2 formed a dimer with HOXB7, and the dimer decreased the expression of c‐FOS by upregulated miR‐221 and miR‐222 in melanoma cells." (PMID 35068042, 2022). "Our results showed that FOS was the gene with the highest fold change in recuryes versus recurno in older melanoma patients." (PMID 33373316, 2020). "In this study we have identified c-FOS as an additional target of miR-221&222 in melanoma, describing the functionality of a HOX/PBX→miR-221&222→c-FOS pathway." (PMID 23400877, 2013). "These melanomas, although expressing low levels of miR-221&222, display a small amount of c-FOS according to its barely phosphorylated status." (PMID 23400877, 2013). "We then assessed the inverse correlation of miR-221&222 and c-FOS expressions by comparing their endogenous levels in normal melanocytes and melanoma cell lines." (PMID 23400877, 2013). "The negative regulation of c-FOS by miR-221&222 was confirmed by western blot analysis in miR-221&222-transduced Me1007 and Me1402/R melanoma cell lines (left)." (PMID 23400877, 2013). "Accordingly, BRAFV600E transfection in Me1007 melanoma induced a striking ERK1/2 activation followed by c-FOS induction." (PMID 23400877, 2013). "Furthermore, knockdown of FOS impaired the cytotoxic effect of NK cells on melanoma cells and the promoting effect of ER-conditioned medium on NK cells." (PMID 37223471, 2023). "In addition to developmental contexts, ERK signalling has also been reported to induce FOS gene expression downstream of oncogenic lesions, such as activating mutations in the BRAF gene, which frequently occur in in human melanomas." (PMID 36077499, 2022). "A further target of miR-221 in melanoma is the AP-1 family transcription factor c-FOS." (PMID 31906510, 2020). "Upregulated FOS might occur in conjunction with activated Wnt pathway to promote melanoma progression in older patients." (PMID 33373316, 2020). "Notably, the opposite expression pattern was observed in the antagomiR-treated A375M and Me665/1 metastatic melanoma cell lines, where a significant induction of c-FOS was obtained by miR-221 and/or -222 abrogation (right)." (PMID 23400877, 2013). "As qRT-PCR (left) and western blot analyses (right) confirmed c-FOS induction in HXR9-treated melanoma cells, we tested whether this up-regulation might be directly responsible for the HXR9-mediated apoptosis." (PMID 23400877, 2013). "As miR-221&222 expressions are directly related with melanoma progression, being almost undetectable in normal human melanocytes and increasingly expressed throughout transformation process, c-FOS was expected to decline from primary to metastatic melanoma." (PMID 23400877, 2013). "Results confirmed lower HOXB7 and higher c-FOS in primary respect to advanced melanomas." (PMID 23400877, 2013). "However, a previous study in B16F-10 melanoma cells showed that piperine was able to inhibit the activation of several transcription factors, including NFκB, c-FOS, cAMP response element binding (CREB) and activating transcription factor 2 (ATF-2)." (PMID 19327174, 2009). "The inhibitory effects on c-FOS, and on genes (p90RSK) encoding proteins that affect CREB phosphorylation, suggest that AZD6244-BEZ235 is a potentially effective approach to overcome recently described mechanisms mediating melanoma resistance to MAPK inhibition." (PMID 26678033, 2016).